TNF (tumor necrosis factor)
Diseases named in the same sentence as TNF in open-access papers (continued):
Sharing a sentence is not in itself a finding about the gene and the disease.
cancer (continued). "Considering that IL6 and TNFα have a close interaction and play essential roles in inflammatory response and cancer long-term outcomes, the combination of them seems to be a potentially more accurate, predictive, and sensitive indicator for predicting cancer prognosis." (PMID 35859928, 2022). "Thus, treating cancer patients with TNFα may eventually give rise to devastating metastasis-promoting effects, and may prove harmful rather than beneficial." (PMID 35663982, 2022). "Elevated levels of cytokines such as tumor necrosis factor alpha (TNF-α), interleukin (IL)-6 and IL-1β, a lipid molecule prostaglandin E2 (PGE2), and chemokines such as CXC chemokine ligand 1 (CXCL1) and CXCL2 in the serum of CRC patients were associated with cancer development and progression." (PMID 35954156, 2022). "Fortunately, the appropriate administration of SPN(NIR-3) and laser irradiation could result in the proper uplift of intracellular oxidative stress, leading to ICD, followed by the release of DAMPs from cancer cells to induce DCs maturation and upregulate cytokines (IL-6 and TNF-α) expression." (PMID 36276646, 2022). "The advanced cancer patients with metastases orally administered with fucoidan demonstrated a significant reduction of main pro-inflammatory cytokines, such as interleukin-1β (IL-1β), IL-6 and tumor necrosis factor-α (TNF-α) after two weeks of fucoidan ingestion." (PMID 36135017, 2022). "Thus, the role of TNF-α in cancer cachexia requires further exploration." (PMID 35319749, 2022). "Importantly, has-mir-324-5p was found to have a significant differential expression in multiple cancer tissues In addition, has-mir-324-5p-targeted genes mainly enriched regulation of Wnt signaling pathway, tumor necrosis factor-mediated signaling pathway, and mRNA metabolic process." (PMID 36246406, 2022). "Particularly, tumour necrosis factor-α (TNF-α), interleukin-1β (IL-1β), and hepatocyte growth factor (HGF) have all been shown to cause mesothelial cell retraction, exposure of the underlying ECM, while facilitating the adhesion of cancer cells to the mesothelial cell monolayer." (PMID 36494669, 2022). "Therefore, we need more specific therapeutic regimens to target TNFR1 and TNFR2, rather than TNF, which can effectively avoid the treatment side effects caused by the non-specific action of TNF and make cancer treatment more efficient." (PMID 35494080, 2022). "Furthermore, when various cytokines that contribute to cancer cachexia—such as TGF‐β, IL‐6, and tumor necrosis factor alpha (TNF‐alpha)—are inhibited, bone mineral density loss is attenuated, most likely by preventing full differentiation of osteoclasts through the RANK–RANKL pathway." (PMID 34791809, 2022). "Our study of occupational exposure to black carbon identified a dose–response relationship between macrophage carbon load and genomic instability in peripheral blood, an established cancer biomarker which may be mediated by a mutagenic cytokine TNF-α in circulation." (PMID 36076291, 2022). "Furthermore, NF-κB is involved in various cancers, such as BC, via several stimulators, including various pro-inflammatory cytokines (IL-1β and TNF-α), growth factors (epidermal growth factor [EGF]), DNA-damaging agents (radiation), and oncogenes (rat sarcoma [RAS])." (PMID 35986321, 2022). "Similarly, decursinol angelate (DA), an AGN-derived compound, inhibited pro-inflammatory cytokines associated with cancer cell proliferation, including TNF-α while decursin blocked lipopolysaccaride-induced expression of MCP-1, IL-8, TNF-α, and IL-1β in cells and attenuated IL-1β and TNF-α." (PMID 36249788, 2022). "We hypothesized that the SIRPγhi CSLCs may regulate CD47 expression in CSLCs and bulk cancer cell population through autocrine or paracrine signaling, particularly as previous studies revealed that cytokines such as TNF-α and IL-1β can stimulate CD47 expression." (PMID 35229723, 2022).
cancer (continued). "Additionally, HSP family members, along with tumor necrosis factor (TNF) ligand family cytokines and Wnt-1 protein involved in Wnt/β-catenin signaling pathway, key players in redox regulation and cancer development, were among the retrieved proteins though at lower significance." (PMID 36670957, 2022). "In addition, the plasticity of microbiota that could slow cancer progression by targeting inflammation was altered by introducing anti‐TNFα." (PMID 35037431, 2022). "Thus, IL-6 and TNFα SNPs could be potential markers of baseline pain intensity and opioid dose requirements in pediatric cancer patients." (PMID 35335997, 2022). "Therefore, TNF‐α levels are elevated in cachectic patients compared with healthy controls, while no significant distinction was noticed between weight‐stable and weight‐losing cancer patients." (PMID 35080147, 2022). "Additionally, when metformin was pretreated, cisplatin caused a change in the expression of genes involved in microRNAs in cancer, cytokine–cytokine receptor interaction, phagosome, osteoclast differentiation, TNF signaling pathway in 48 h metformin-pretreated group." (PMID 36661507, 2022). "Some of the significant cancer hallmark terms are inflammatory response (CD14, CD69, IL10RA), KRAS signaling up (CD37, IL10RA, GPNMB), IL-6/JAK/STAT3 signaling (CD14, CSF2RB), Interferon Gamma Response (CD69, CSF2RB, IL10RA, VCAM1, SLAMF7), TNF-alpha Signaling via NF-kB (CD69)." (PMID 35486660, 2022). "Indeed, a study carried out by transducing different cancer cell lines showed how their dynamics upon TNF-α could differ." (PMID 35844496, 2022). "Anti-TNF-α antibodies might be an effective anti-cancer therapy." (PMID 35493517, 2022). "Additionally, the TNF-α NF-κB signaling pathway and complement gene sets were enriched in cancer." (PMID 36429712, 2022). "In one study, a water JCo extract inactivated the PI3K–Akt pathway in cancer cells, and our data revealed that JCo extract suppressed NFκB expression and the downstream expression of chemokines and cytokines such as TNF‐α, IL‐1β, IL‐6, and CCL2 in the rat renal cell line NRK‐52E." (PMID 36249972, 2022). "Anti-TNFα therapies failed to prevent weight loss in patients with advanced cancer cachexia." (PMID 35646636, 2022). "We also analyzed the differences in some cancer-related pathways between high- and low-FerroScore groups, and the results showed that the low-FerrScore group was positively correlated with iron uptake and ferroptosis, while negatively correlated with TNF pathways." (PMID 36349201, 2022). "The inflammation process remains a driving force in the progression of cancer, promoting its development through the production of inflammatory cytokines, with microbial dysbiosis leading to increased concentrations of interleukin (IL)-1, 6, 10, and tumor necrosis factor alpha (TNF-α)." (PMID 36428774, 2022). "However, its relevance in adipose atrophy is still ambiguous as serum TNF-α was unchanged in cachectic cancer patients and did not correlate with weight loss." (PMID 35646636, 2022). "Indeed, since chronic inflammation is well known to play a critical role in cancer progression, development, and survival, the finding of decreases in a variety of cytokines (particularly IL-6, and TNF-α) may have similar implications." (PMID 35935260, 2022). "Indeed, the use of anti-TNF drugs to treat cancer has a long and interesting history." (PMID 35844493, 2022). "Moreover, TNFα could improve the efficacy of drugs/chemotherapy in cancer treatment, e.g., by promoting blood vessel permeability." (PMID 35663982, 2022). "Additionally, decreased albumin levels demonstrate an increased inflammatory status with elevated levels of cytokines, such as tumor necrosis factor-alpha, IL-1, and IL-6, which may contribute to cancer progression." (PMID 35915403, 2022).
cancer (continued). "For example, it was found that high concentration of IL-35 in CRC could inhibit the cancer cell migration, invasion and proliferation, more importantly, suppress the cancer stem cells; also, the concentration of TNF-α was found to be negatively correlated with the stage in CRC." (PMID 35296257, 2022). "KEGG analysis showed that the PHLDA family members and their 600 co-expressed genes may play important roles in various pathways related to the occurrence and development of cancer, such as the “Hippo signaling pathway”, “apoptosis”, the “TNF signaling pathway”, and the “MAPK signaling pathway”." (PMID 36142223, 2022). "Our study demonstrated that the RPM scores across 12 types of cancers were significantly associated with TMB, MSI, CD8+ T-cell infiltration, immune checkpoint molecules (PD-1/PD-L1, CTLA4), and cytokine (IFN-γ, TGF-β, and TNF-α) expression, which are key predictors of immunotherapy response." (PMID 35493519, 2022). "However, TNFα also induces NFκB activation that promotes cancer growth." (PMID 34025421, 2021). "Moreover, TNF-α is chronically produced in various types of cancer." (PMID 34287243, 2021). "In addition, TNF-α facilitates the proliferation of cancer cells in the immune microenvironment." (PMID 34572719, 2021). "Finally, KEGG analysis revealed that the active ingredients of PBL could affect multi-pathways, including chemical carcinogenesis, TNF signaling pathway, drug metabolism—cytochrome P450 and pathways in cancer, etc.." (PMID 34836315, 2021). "However, TNF is likely to play an oncogenic role in multiple types of cancer, including NSCLC." (PMID 33373873, 2021). "Stromal cells and cancer cells could both be sources of TNF-α." (PMID 34497832, 2021). "Furthermore, increased expression of KRAB-ZNFs is significantly associated with the downregulation of many proinflammatory signaling pathways in KIRC, especially those mediated by interferons, IL2, IL6, or TNF-α, which was previously shown to enhance cancer stemness maintenance." (PMID 34638319, 2021). "Interestingly, the cytokines IL-6, IL-8 and TNF-α that were detected in the supernatants of the SeNps-treated cells, have been previously reported to be released by cancer cells undergoing ICD and to be involved in the signalling of dendritic and natural killer cells." (PMID 34771499, 2021). "Previous in vitro study on epithelial cancer cells has shown that cancer cell lines of different origins—when incubated with either supernatant derived from a mixed lymphocyte population or a mix of inflammatory cytokines (TNFα, TGFβ and IFNγ)—undergo a series of changes typical of the EMT." (PMID 35096592, 2021). "Finally, TNF-α, a master regulator of the host immune response, may or may not convey protective effects during carcinogenesis in different cancer types depending on the type of receptors recruited (i.e., TNFR1 or TNFR2)." (PMID 34205944, 2021). "Likewise, activation of cytotoxic lymphocytes in cancer immunotherapy triggers TNF release." (PMID 33484626, 2021). "CD treatment is based on the use of immunosuppressors, which do not seem to increase the risk of developing cancer, beside a slightly increased risk of lymphoproliferative and cutaneous malignancies associated with thiopurines and tumor necrosis factor (TNF) antagonists." (PMID 33540674, 2021). "However, the potential involvement of AWP1 in cancer progression in response to TNF-α is still unknown." (PMID 33816268, 2021). "In addition, KEGG analysis showed enrichment in the cancer pathways, protein processing in the endoplasmic reticulum, and the TNF signaling pathway, which suggested that autophagy gene dysregulation may participate in cancer biological processes." (PMID 33976960, 2021). "Additionally, IFN-γ/IL-4 and TNF-α/IL-4 ratios were significantly higher in cancer patients." (PMID 34012451, 2021).
cancer (continued). "First, consistent with the role of inflammation in cancer development and progression, we observed a significant upregulation of Th1 pro-inflammatory cytokines in both solid and haematological malignancy patients compared to HCWs, including TNF-α, IL-6, and IL-1Ra." (PMID 34830872, 2021). "However, high levels of TNF- α, IL-2R, IL-6, and IL-8 did not raise the risk of death in non-cancer patients." (PMID 33735106, 2021). "Furthermore, using the anti-IFN-γ and anti-TNF-α neutralizing antibodies to block these soluble factors (IFN-γ or TNF-α) in the CM of the educated MPE-Mφ could reduce the anti-cancer effects, individually and synergistically." (PMID 33175182, 2021). "Since cIAPs are required for TNF induced activation of the pro-survival canonical NF-κB pathway and to prevent TNF induced death, Smac-mimetics can cause TNF induced apoptosis of a subset of cancers by simultaneously activating non-canonical NF-κB and inhibiting canonical NF-κB." (PMID 34572737, 2021). "However, leptin may expand cancer cells through the production of cytokines by macrophages and also upregulate the pro-inflammatory cytokines such as TNF-α and IL-6 and stimulated the macrophage function." (PMID 34360753, 2021). "Furthermore, subgroup analysis according to the type of anti-TNF agent, did not demonstrate any statistically significant association between adalimumab, golimumab, infliximab, certolizumab, or etanercept and cancer risk." (PMID 34790122, 2021). "However, these approaches are, as the historical attempts to use recombinant TNF-α in cancer patients, not specific to cancer cells, with a high risk of off-target effects." (PMID 34712661, 2021). "Thus, the anti-inflammatory effect of flavonoids inhibits angiogenesis of cancer cells by decreasing inflammatory cytokines such as tumor necrosis factor-alpha, interleukin (IL)-1β, and IL-6, and the anti-estrogen effect prevents metastasis of cancer cells by decreasing aromatase activity." (PMID 34578927, 2021). "Indeed, in several cancer types, high levels of tumor necrosis factor (TNF) were detected." (PMID 34638416, 2021). "Therefore, our results show that the PGG effect as an apoptotic inducer through TNF increased expression may have a clinical significance in cancer treatment." (PMID 33707603, 2021). "Finally, CD4 T cells can also mediate direct cytotoxic responses through IFN-γ and TNF secretion, production of cytolytic granules or expressing ligand of tumor necrosis factor (TNF) superfamily molecules including FasL or TRAIL leading to cancer cell apoptosis when engaged with their receptors." (PMID 33329566, 2020). "KEGG pathway analysis showed that lncRNA EPB41L4A-AS1 was mainly involved in four pathways, including RNA transport, MAPK signaling pathway, transcriptional misregulation in cancer, and TNF signaling pathway, suggesting that lncRNA EPB41L4A-AS1 may function as a regulator in the metabolism of NSCLC." (PMID 33193600, 2020). "In addition to augmenting SMAC mimetic-induced apoptosis, TNF-α could have broader effects on the immune system by stimulating cytotoxic T cells to act against cancer cells." (PMID 33334024, 2020). "Also as extracts of plants may activate the immune system of the hosts and kill cancer cells, one can consider testing the concentrations of various cytokines, tumor necrosis factor, etc., before and after administration of PV." (PMID 32295069, 2020). "However, both TNF-α and IL-1β also upregulate Oct4 expression in cancer cells, which may counterbalance the antitumor activity of M1 macrophages." (PMID 32487125, 2020). "Therefore, M-CSF is speculated to affect the production of IL-6, TNF-α, and TGF-β via the activation of macrophages, and thereby associated with cancer-related inflammation symptoms." (PMID 33050250, 2020).
cancer (continued). "However, we could imagine that stromal cells around the tumor, such as fibroblasts or endothelial cells, could secrete many soluble factors such as TGF-β or TNF-α in order to promote invadosome formation by cancer cells." (PMID 32984031, 2020). "Moreover, this metabolic responses seem to be mediated by secretion of pro-inflammatory cytokines from cancer cells and also from the immune system of the host, including tumor necrosis factor (TNF), interferon-gamma (IFN-γ), and several interleukins (IL-6, IL-1β)." (PMID 32230855, 2020). "Indeed, visceral obesity, considering the adipocytes and infiltrated immune cells, is particularly related to the increase concentration of this cytokines (TNF-α, IL-6, adiponectin, visfatin and so on), evidencing the important link between adipose tissue, inflammation and cancer." (PMID 33371214, 2020). "Also, it was shown that Apigenin is able to block tumor necrosis factor-alpha (TNFα) pathway in MDA- MB231 cancer cells; therefore, the following release of chemokines such as CCL2, granulocyte-macrophage colony-stimulating factor (GMCSF), IL-1α and IL-6 is inhibited." (PMID 32952942, 2020). "The systemic inflammatory response from cancer cells promotes the infiltration of neutrophils, which benefits cancer progression via secreting interleukin-2 (IL-2), interleukin-6 (IL-6), interleukin-10 (IL-10), tumor necrosis factor α (TNF-α) and vascular endothelia growth factor (VEGF)." (PMID 32510138, 2020). "Cytokines such as TNF, growth factors including PDGFA and NRG1, and others like WNT10A were identified to interact with their receptors on neurons or other cells such as microglial cells to directly or indirectly sensitize neuropathic pain associated with cancers." (PMID 32434423, 2020). "Similarly, the HBV−/nondrinker cohort also contained a greater number of significantly associated cancer pathways, including the ATF-2 transcription factor network and TNF signaling pathway, in comparison to immune pathways, where it was only associated with cytokine-cytokine receptor interaction." (PMID 32575865, 2020). "However, TNF, by acting directly on cancer cells, can induce apoptosis and inhibit proliferation, processes that could be used for cancer therapy." (PMID 31861498, 2019). "Interestingly, these authors subsequently showed that in vitro cancer cell proliferation and invasion could also be inhibited by dysfunctional ECs (activated by TNF-α, VEGFA, and FGF2), to an extent even greater than by the quiescent ECs." (PMID 31656195, 2019). "Furthermore, it has been reported that TNF-α could induce autophagy in cancer cells when NF-κB signaling is inhibited." (PMID 31540489, 2019). "In addition, we demonstrated that the cell fusion frequency of MDA-MB-435 cancer cells with M13SV1 breast epithelial cells was markedly increased by TNF-α, which in turn could be blocked by the administration of the antibiotic minocycline." (PMID 31266502, 2019). "Given the association between Pgp and apoptosis-related proteins, and that TNF-α is associated with the cancer microenvironment, we hypothesized that Pgp and TNF-α could contribute to cellular malignancy maintenance and stimulate a phenotype switch in non-cancer cells." (PMID 31137684, 2019). "Thus, downstream molecules of TNFα signaling which are cancer-specific might be better therapeutic targets to prevent systemic toxicity." (PMID 30760700, 2019). "Thus, MADD being an adaptor protein and possessing the ability to activate ERK in TNFα signaling might have a role in cancer metastasis, which needs to be investigated." (PMID 30760700, 2019). "Because transcription of TNF-α is regulated by the promoter region of the TNF-α gene, polymorphisms located in this region could regulate TNF-α production and thus affect the risk of cancer." (PMID 31244280, 2019).